RNU6-650P (RNA, U6 small nuclear 650, pseudogene)
Gene: Small nuclear RNA gene on chromosome 7 (149,033,057 to 149,033,167, forward strand). Ensembl gene ENSG00000202528.
Homologues: Orthologues: macaque U6 (91% identical), rabbit U6 (66% identical). Paralogues in human: RNU6-552P (76% identical), RNU6-16P (74% identical), RNU6-1152P (73% identical), RNU6-14P (73% identical), RNU6-737P (73% identical), RNU6-820P (73% identical), RNU6-960P (73% identical), RNU6-1 (72% identical), RNU6-11P (72% identical), RNU6-12P (72% identical), RNU6-13P (72% identical), RNU6-144P (72% identical), and 1285 more.